SPOP (speckle type BTB/POZ protein)
Diseases named in the same sentence as SPOP in open-access papers (continued):
Sharing a sentence is not in itself a finding about the gene and the disease.
prostate carcinoma (continued). "The gene encoding the E3 ubiquitin ligase substrate-binding adaptor SPOP is frequently mutated in prostate cancer (PCa), but how SPOP functions as a tumor suppressor and contributes to PCa pathogenesis remains poorly understood." (PMID 35194188, 2022). "It is worth noting that prostate cancer and endometrial cancer caused by somatic SPOP variants tend to have alterations in the MATH domain." (PMID 36259278, 2022). "Loss-of-function mutations in SPOP occur in 10% of primary prostate cancer with a high Gleason grade and poor prognosis." (PMID 35252555, 2022). "SPOP-inactivating mutations in prostate cancer cells stabilize Brd4 and confer resistance to BETi, while SPOP-activating mutations in colorectal cancer cells with reduced Brd4 expression are exquisitely sensitive to BETi and prone to apoptosis." (PMID 36539410, 2022). "Investigation of the pathophysiological functions of SPOP has attracted extensive attention in recent years because of its high mutation frequency in prostate cancer (PCa) (5–15%) and endometrial cancer (EC) (8–10%), two hormone-related cancers." (PMID 36585710, 2022). "Of note, the gene encoding the E3 ubiquitin ligase substrate-binding adaptor SPOP is frequently mutated in primary prostate cancer that leads to accumulations of multiple onco-proteins, including BRD4, AR, NANOG, Caprin1, or GLI." (PMID 36357379, 2022). "Owing to a relatively high frequency of SPOP somatic mutations in prostate cancer and the deadly nature of metastasis, our results have a clear clinical implication." (PMID 34322378, 2021). "Although SPOP is broadly recognized as a tumor suppressor in prostate cancer and SPOP mutations are associated with high frequency of genomic rearrangements, the molecular mechanisms by which SPOP mutations promote genome instability remain poorly understood." (PMID 34599168, 2021). "Taken together, these findings offer mechanistic insights into how SPOP mutations influence prostate cancer." (PMID 34630112, 2021). "Mutations in SPOP E3 ligase gene are reportedly associated with genome-wide DNA hypermethylation in prostate cancer (PCa) although the underlying mechanisms remain elusive." (PMID 34588438, 2021). "Speckle type Poz Protein (SPOP) is an E3 ubiquitin ligase adaptor that is often mutated in prostate cancer." (PMID 34322378, 2021). "Whole-genome and exome sequencing of cancer patient samples have shown that SPOP is the most frequently mutated gene in primary prostate cancer, suggesting that patients with SPOP mutations represent an important subtype of prostate cancer." (PMID 34599168, 2021). "In prostate cancer, specific SPOP mutation can also confer resistance to BET-BD inhibitors through stabilization of BRD4 and enhanced Akt–mTORC1 activation as a result of BRD4 stabilization." (PMID 34540900, 2021). "Recently, the genome sequencing studies have disclosed that SPOP is one of the most frequently mutated genes (up to 15% of cases) in prostate cancers, among which most of SPOP somatic mutations occurred within its MATH domain." (PMID 34353330, 2021). "Mutation of SPOP and the resulting dysregulation of ubiquitin-proteasome pathways play an important role in the pathogenesis and progression of endometrial and prostate cancers, whereas its overexpression and mislocalization are correlated with kidney cancer." (PMID 34235141, 2021). "Recent studies on prostate cancer patients have revealed that the SPOP gene as the most common recurrent point mutations, with 8%–15% of the patient population carrying a somatic mutation in this gene." (PMID 34322378, 2021). "Pathologically, prostate cancer patients associated mutations of SPOP impaired PDK1 degradation and thus activated the AKT kinase, resulting in tumor malignancies." (PMID 34353330, 2021). "SPOP mutations in prostate cancers mainly occur in the MATH domain, which is responsible for substrate binding." (PMID 34599168, 2021).
prostate carcinoma (continued). "Similar study has also demonstrated that SPOP-mutated prostate cancer cell lines and patient-derived organoids were intrinsically resistant to BET inhibitor-induced growth arrest and apoptosis." (PMID 34630112, 2021). "In this study, we sequenced the SPOP gene in 198 prostate cancer patients and found 16 mutations in the cohort." (PMID 34322378, 2021). "Gene fusions involving the ERG transcription factor and point mutations in the ubiquitin ligase adaptor SPOP are two truncal mutations that are mutually exclusively present in prostate cancer." (PMID 33531470, 2021). "F102, W131, and F133 are frequently mutated in prostate cancers, which results in reduced affinity of SPOP for substrate proteins." (PMID 33894201, 2021). "Our observations are supported by previous reports, which showed that SPOP mutations increased the motility of prostate cancer cell in vitro and in vivo." (PMID 34322378, 2021). "Our data demonstrate that SPOP-mutated prostate cancer cells are hypersensitive to ATR inhibition in vitro and in vivo." (PMID 34599168, 2021). "Collectively, we demonstrate that SPOP knockdown is associated with a more mesenchymal phenotype in prostate cancer cells." (PMID 34322378, 2021). "The Speckle Type BTB/POZ protein (SPOP) is a Cul1 adapter that is mutated in 10% of prostate cancers." (PMID 33906413, 2021). "A dominant negative effect probably causes SPOP mutant forms associated with prostate cancer to be defective in promoting INF2 ubiquitination, resulting in increased localization of INF2 at the endoplasmic reticulum." (PMID 34685534, 2021). "In aggregate, the data support an antagonistic relationship between oncogenic activation of ERG and a loss of SPOP function in prostate cancer cells." (PMID 33531470, 2021). "In prostate cancer, SPOP mutation abrogates its interaction with the SRC-3 protein and subsequent regulation on AR transcription, leading to tumor progression and resistance to androgen deprivation therapies." (PMID 34235141, 2021). "The clinical impact of prostate cancer-associated SPOP mutants, including F133V, on genome stability was investigated by using the whole genome sequence (WGS) database derived from prostate cancer patients." (PMID 33023230, 2020). "Speckle-type POZ (pox virus and zinc finger protein) protein (SPOP) is the most commonly mutated gene in prostate cancer (PCa)." (PMID 32512734, 2020). "Overexpression of prostate cancer-associated SPOP mutants (e.g., Y87C, and F133V) increased the amount of TOP2A, but not TOP1, in the nuclei as well as the drastic accumulation of γH2AX in the nuclei." (PMID 33023230, 2020). "Expression of prostate cancer-associated SPOP mutants, Y87N, K129E, or F133V in DU145 cells and PC-3 cells sensitized to IR." (PMID 33023230, 2020). "In contrast to prostate cancer-associated SPOP mutants, the endometrial cancer-associated SPOP mutations are located outside the substrate-interacting cleft of the MATH domain." (PMID 33023230, 2020). "SPOP mutants associated with prostate cancer fail to interact with and ubiquitinate their substrates, leading to the accumulation of oncogenic substrate proteins such as androgen receptor (AR), BRD2, and BRD4." (PMID 33023230, 2020). "On the contrary, chromodomain helicase DNA binding protein 1 (CHD1) deletion and SPOP mutations frequently co-occur in prostate cancer, and these tumours are highly sensitive to androgen biosynthesis inhibitors." (PMID 32365491, 2020). "Depletion of SPOP in AR-positive, prostate cancer C4-2 cells caused an accumulation γH2AX in the nuclei." (PMID 33023230, 2020). "Biochemically, prostate cancer-associated SPOP mutants (e.g., Y87C, and F133V) lose the ability to bind to substrates." (PMID 33023230, 2020). "Knockdown of SPOP or expression of prostate cancer-associated SPOP mutants sensitized prostate cancer cells to PARP inhibitor, olaparib, as was seen in BRCA1-depleted cells." (PMID 33023230, 2020).
prostate carcinoma (continued). "Since these mutants can interact with CUL3 as well as wild-type SPOP, the prostate cancer-associated SPOP mutants serve as dominant-negative mutants." (PMID 33023230, 2020). "In here, we unveil a strong association between ZBTB38 and several clinico-pathological and genomic features of prostate cancer, including a strong association with SPOP and SPOPL alterations." (PMID 32365491, 2020). "SPOP, a substrate binding adaptor of E3 ubiquitin ligase Cullin3, is frequently mutated in human prostate cancer (PCa)." (PMID 32364525, 2020). "The exosome sequences revealed that SPOP is heterogeneously mutated in approximately 10–15% of patients with prostate cancer." (PMID 33023230, 2020). "In contrast, LLPS is disrupted by expression of prostate cancer-associated SPOP mutants, resulting in the decreased accessibility of substrates to the phase separation." (PMID 33023230, 2020). "Another prostate cancer-associated mutation of SPOP, Q165P at the edge of the MATH domain, impairs dimerization of SPOP, resulting in the inhibition of substrate degradation." (PMID 33023230, 2020). "SPOP mutations occur early in the natural history of prostate cancer (PCa) and are present in about 10% of both clinically localized and metastatic disease, thus representing the most common non-synonymous mutations in PCa." (PMID 32512734, 2020). "A paradigm shift in the understanding of SPOP occurred when point mutations were identified in the MATH domain of patients with prostate cancer." (PMID 33023230, 2020). "The three-dimensional structures of SPOP mutants would differ between the prostate cancer-associated ones and the endometrial cancer-associated ones." (PMID 33023230, 2020). "Approximately 10–15% of prostate cancer patients possess point mutations in the substrate-binding domain of SPOP." (PMID 33023230, 2020). "SPOP has been extensively studied as a tumor suppressor and is a frequently mutated hotspot, most notably in prostate cancer." (PMID 32365080, 2020). "Taken together, these data demonstrate that WT SPOP suppresses SG assembly, while the prostate cancer-associated SPOP mutants enhances SG assembly." (PMID 31771591, 2019). "SPOP WT suppresses SG assembly, while the prostate cancer-associated mutants enhance SG assembly in a Caprin1-dependent manner." (PMID 31771591, 2019). "The vast majority of the SPOP mutations detected thus far in prostate cancer primarily occur in the MATH domain, which is responsible for substrate binding." (PMID 31771591, 2019). "SPOP is the most frequently mutated gene in primary prostate cancer (PCa) and its mutation rate ranges from 10 to 15% of human PCa depending on the patient cohorts studied." (PMID 31559706, 2019). "Two recent studies have explored the mechanisms through which SPOP mutations promote stemness features in prostate cancer cells." (PMID 31366128, 2019). "On the opposite, ELOVL2 upregulation in prostate cancer has been associated with the oncogenic effect of SPOP loss of function mutations." (PMID 31619292, 2019). "SPOP mutation compromises of ubiquitin-mediated PD-L1 degradation leading to increased PD-L1 levels and reduced numbers of infiltrating lymphocytes in prostate cancers." (PMID 31366128, 2019). "Next, we investigated the impact of prostate cancer-associated mutants of SPOP on Caprin1 localization." (PMID 31771591, 2019). "We investigated the role of SPOP mutations in aberrant activation of the SG in prostate cancer and explored the relevanve of the mechanism in therapy resistance." (PMID 31771591, 2019). "SPOP‐mutated prostate cancer possesses distinct molecular features such as resistance to BET inhibitors." (PMID 31559706, 2019). "Collectively, these data suggest that SPOP mutations result in elevated Caprin1 protein abundance that associated with prostate cancer progression." (PMID 31771591, 2019).
prostate carcinoma (continued). "AR showed a broad spectrum of activity between genomic subtypes: ETS fusion-positive prostate cancers display a variable AR transcriptional activity; tumors with SPOP or FOXA1 mutations had the highest AR transcriptional activity." (PMID 31366128, 2019). "The gene encoding the E3 ubiquitin ligase substrate-binding adaptor SPOP is frequently mutated in primary prostate cancer, but how SPOP mutations contribute to prostate cancer pathogenesis remains poorly understood." (PMID 31771591, 2019). "CULLIN3‐based E3 ubiquitin ligase substrate‐binding adaptor gene SPOP is frequently mutated in prostate cancer (PCa)." (PMID 31559706, 2019). "SPOP‐mutated subtype of prostate cancer bears several unique features such as aberrant AKT and AR co‐activation and BET inhibitor resistance." (PMID 31559706, 2019). "Particularly in prostate cancer, previous publications had reported an abundance of substrate proteins because of recurrent SPOP mutations." (PMID 31577764, 2019). "Increasing evidence indicates that SPOP mutated prostate cancer has a unique molecular and phenotypical features." (PMID 31771591, 2019). "WT SPOP suppresses SG assembly and promotes stress-induced cell death in prostate cancer cells by targeting Caprin1 for ubiquitin-dependent degradation, and this effect is abrogated by prostate cancer-associated SPOP mutations." (PMID 31771591, 2019). "In contrast, forced expression of prostate cancer-associated mutants of SPOP moderately increased SG assembly, probably by acting through a dominant-negative effect to inhibit endogenous SPOP." (PMID 31771591, 2019). "Recent studies have better clarified the potential role of SPOP mutations to prostate cancer pathogenesis." (PMID 31366128, 2019). "Collectively, we identified a novel SPOP mutation-driven protumorigenic process in prostate cancer by upregulating SG assembly." (PMID 31771591, 2019). "SPOP mutations lead to increased prostate cancer cell proliferation, invasion and immune escape in vivo, implying that SPOP mutations are driving molecular events in prostate cancer initiation and progression." (PMID 31771591, 2019). "SPOP mutations in prostate cancer attenuate its binding ability to BET proteins and decreased proteasomal degradation." (PMID 31311566, 2019). "According to these observations it was concluded that the SPOP protein plays a key tumor suppressor role in prostate cancer cells, but this effect is lost by the prostate cancer-associated SPOP mutants." (PMID 31366128, 2019). "SPOP mutations cause resistance to cellular stress induced by chemtherapeutic drug such as docetaxel in prostate cancer." (PMID 31771591, 2019). "Our results provide a novel functional link between SPOP mutation and upregulation of SG assembly in prostate cancer." (PMID 31771591, 2019). "Alternatively, prostate cancer is classified by ETS transcription family fusions or mutations in Speckle-type POZ protein (SPOP)." (PMID 30939845, 2019). "This is extremely beneficial as mutations in SPOP lead to a type of prostate tumor thought to be involved in about 15% of all prostate cancers." (PMID 31632973, 2019). "Together our findings demonstrate that at least some prostate cancer-associated mutants of SPOP are defective in regulating ATF2 protein." (PMID 29996942, 2018). "AKT‐mTOR and androgen receptor (AR) signaling pathways are aberrantly activated in prostate cancer due to frequent PTEN deletions or SPOP mutations." (PMID 29523594, 2018). "Recurrent gene fusions in the oncogenic transcription factor ERG, present in 40% to 50% of prostate cancers, define one such subclass, while a second distinct class, comprising 10% of prostate cancers, is defined by recurrent mutations in SPOP." (PMID 29202479, 2018). "Both AKT‐mTOR and androgen receptor (AR) signaling pathways are aberrantly activated in prostate cancer due to PTEN deletion or SPOP mutation, two genetic lesions occurring in up to 80% of advanced prostate cancer." (PMID 29523594, 2018).
prostate carcinoma (continued). "In prostate cancer, only one allele of the SPOP gene is mutated, and SPOP mutants exert their tumor-promoting functions in a dominant-negative manner to inhibit wild-type SPOP." (PMID 29996942, 2018). "Although SPOP mutation is now recognized as a distinct molecular feature in a subtype of prostate cancer, the functional impact of these mutations on prostate tumorigenesis and metastasis is still not fully understood." (PMID 29996942, 2018). "Mutations in SPOP lead to genomics instability and are identified as driver events resulting in tumorigenesis of prostate carcinoma via coordination with PI3K/mTOR and AR (Androgen Receptor) pathway in mouse." (PMID 29986747, 2018). "Most importantly, the Cancer Genome Atlas (TCGA) data demonstrate that SPOP‐mutated prostate cancers exhibit the highest AR activity among all molecular subtypes of prostate cancer examined." (PMID 29523594, 2018). "Our results provide a functional insight into the underlying molecular mechanism of prostate cancer with SPOP mutations." (PMID 29996942, 2018). "Pharmacological inhibition of HDAC3 using a selective HDAC3 inhibitor RGFP966 inhibits growth of both PTEN‐deficient and SPOP‐mutated prostate cancer cells in culture, patient‐derived organoids and xenografts in mice." (PMID 29523594, 2018). "Intriguingly, all the mutations in SPOP gene detected in prostate cancer thus far affect the binding of SPOP with its substrates." (PMID 29523594, 2018). "Prostate cancer-associated SPOP mutants fail to interact with and promote the degradation of BET proteins, leading to their increased abundance and causing a resistance to BET inhibitors in SPOP-mutant prostate cancer." (PMID 30150556, 2018). "Previous studies reported that the expression of the prostate cancer-associated SPOP mutant or SPOP knockdown increases prostate cancer cell proliferation, migration and invasion." (PMID 29996942, 2018). "The aim of this work was to investigate how SPOP mutations contribute to prostate cancer development and progression." (PMID 29996942, 2018). "Strikingly, prostate cancer-associated mutants of SPOP are defective in promoting ATF2 degradation in prostate cancer cells and contribute to facilitating prostate cancer cell proliferation, migration and invasion." (PMID 29996942, 2018). "Somatic mutation analyses of cancer genomes have indicated that the SPOP gene is always mutated in several human cancers; for example, approximately 10% of prostate cancers, 8% of endometrial carcinoma and 2.2% of colorectal cancer reveal SPOP gene mutations." (PMID 30607139, 2018). "The SPOP mutation frequency in our samples is consistent with previous findings in different cohorts of prostate cancer." (PMID 29996942, 2018). "To examine the effect of SPOP mutations on ATF2 protein levels in specimens from individuals with prostate cancer, we analyzed ATF2 protein levels in a cohort for which a total of 90 primary prostate tumor samples were available." (PMID 29996942, 2018). "TRIM24 is an effector substrate of the E3 ubiquitin ligase adaptor SPOP and becomes stabilized in prostate cancer (PCa) with SPOP mutations." (PMID 30479348, 2018). "The most frequent SPOP mutations in prostate cancer are located at seven distinct AA residues (e.g., Y87, F102, W131 and F133) clustered in the MATH domain (AA 31–166)." (PMID 28810879, 2017). "All the SPOP mutations detected thus far in prostate cancers exclusively occur in the MATH domain, which is responsible for substrate binding." (PMID 28448495, 2017). "The majority of SPOP mutations in EC and in prostate cancer localize to the MATH domain, which binds proteins that are targeted for ubiquitination and proteasomal degradation." (PMID 29137450, 2017). "Next, we investigated the impact of prostate cancer-associated mutants of SPOP on INF2 localization." (PMID 28448495, 2017).